DDB1 (damage specific DNA binding protein 1)
Diseases named in the same sentence as DDB1 in open-access papers (continued):
Sharing a sentence is not in itself a finding about the gene and the disease.
tumor (35 papers, 2007 to 2026). "By treating CSCs with nitazoxanide, a known inhibitor of DDB1, we observed a marked reduction in B7-H3 expression, alongside diminished tumor sphere formation and migration capacity." (PMID 40230524, 2025). "While the involvement of DDB1 in tumour progression through DNA repair and RNA transcriptional regulation has been reported, its expression and role in LUAD remain to be elucidated." (PMID 40404474, 2025). "Functional assays revealed that targeting DDB1 with nitazoxanide significantly downregulated B7-H3 expression, subsequently impairing tumor sphere formation and cell migration in breast CSCs." (PMID 40230524, 2025). "Exosomal miR-3200-3p, originating from VEGFR suppressed tumor cells, had the capacity to target DDB1, thereby promoting T cell senescence." (PMID 39911664, 2024). "A previous study investigated the role of DDB1 in PDAC and reported DDB1 as a tumor-promoting factor through the positive regulation of cancer cell proliferation, EMT and chemoresistance." (PMID 36568213, 2022). "The results showed that transcription of CUL4A and DDB1 was significantly higher in tumor tissue than in normal tissue." (PMID 36481655, 2022). "Only a single up-regulated gene, DCAF13 (DDB1 and CUL4 associated factor 13) (boxed in orange) was found to be correlated with the only up-regulated tumor capsule specific lncRNA, DCAF13P3 (boxed in orange)." (PMID 32636408, 2020). "In this study, we reported that DDB1 functions as a tumor-promoting factor in PDAC by regulating cancer cell proliferation, epithelial-mesenchymal transition (EMT) and chemoresistance." (PMID 31842285, 2019). "The decreased tumor sizes and low Ki-67 expression in tumor xenograft models further indicated that DDB1 regulates GEM metabolism by affecting dCK, which expands the size of the dNTP pools." (PMID 31842285, 2019). "MTUS1 regulates the cell cycle by acting as a tumor suppressor and DDB1 is involved in nucleotide excision repair." (PMID 22664934, 2012). "In summary, we demonstrated that circ_0004470 regulates BPDE-induced DNA damage by interacting with XPC and DDB1, thereby facilitating the acquisition of cellular oncological phenotypes, including malignant proliferation, metastasis, and tumor-forming capacity." (PMID 40157540, 2025). "AMBRA1, which was initially reported to be essential for nervous system development via autophagy and cell proliferation control, also functions as a tumor suppressor by regulating the ubiquitination of D-type cyclins through interaction with DDB1-Cullin4A/4 B E3 ligase." (PMID 40734673, 2025). "Notably, transcriptomic data and RTqPCR results demonstrated that while PUM2 and HIF3A were highly expressed in normal tissues, DDB1 showed increased expression in tumor tissues, with CUL1, COPS2, and UBE2D3 remaining unchanged." (PMID 40524221, 2025). "Tumor mutation burden analysis indicated that in 433 STAD samples, 73 samples showed altered mutation frequencies in PRG signatures, with mutation rates of 4% for COL8A1, 3% for DDB1, 3% for PARP1, and 3% for ESR2." (PMID 41004487, 2025). "Notably, DDB1 exhibited statistically significant overexpression in tumor tissues, suggesting its pivotal role in modulating key biological processes and contributing to the complex progression of BLCA." (PMID 40524221, 2025). "Interestingly, the mainly nuclear expressed E3 ligase receptor, DCAF1, a part of the CRLDCAF1 and EDVP complex, showed similar tumor essentiality in the test set to DDB1." (PMID 38177131, 2024). "DDB1 is involved in DNA repairing and has been related to tumor suppression." (PMID 35204174, 2022). "Moreover, higher CRL4CUL4A/DDB1 nuclear staining was also observed in platinum-resistant patient tumor samples and was correlated with reduced overall and disease-free survival (DFS)." (PMID 36481655, 2022). "Knockdown either CUL4A/4B or DDB1 significantly inhibits tumor cell growth in vitro and in vivo." (PMID 32140073, 2020).
tumor (continued). "In addition, PIN1 and DDB1 proteins, also known to regulate HBx protein stability, were significantly overexpressed in tumor tissues in 35 (87.5%) samples and in 19 (42.2%) samples, respectively." (PMID 25361011, 2014). "We recently demonstrated that hepatocyte-specific deletion of DDB1, an adaptor protein for Cullin4 ubiquitin ligase, permanently blocks the hepatocytes from self-renewing, resulting in compensatory regeneration of new DDB1-expressing hepatocytes and progressive tumor development." (PMID 22384083, 2012). "DDB1 and CUL4‐associated factor 7 (DCAF7) is a WD‐repeat adaptor that recruits substrates to the CUL4DDB1 ubiquitinligase complex, but its pan‐cancer relevance and mechanistic contribution to tumor progression remain unclear." (PMID 41472554, 2026). "Complementary GO, KEGG, and GSEA analyses revealed that the DDB1 gene is highly correlated with apoptotic processes across species, mismatch repair, embryogenesis, negative regulation of sodium transmembrane transporter activity, and several tumor-activating signaling pathways." (PMID 40524221, 2025). "Of note, previous studies identified that Wdr4 exerts multiple functions, such as regulating tumor microenvironments, stabilizing tRNA, and maintaining genome stability, through interacting with different partners/effectors, including DDB1/PML, METTL1, and FEN1, individually." (PMID 36681682, 2023). "Inhibition of DDB1 with NTZ significantly reduced B7-H3 expression in CSCs, which corresponded with a decrease in tumor sphere formation and cell migration." (PMID 40230524, 2025). "Further investigations revealed that knockdown of the TFs candidates—DDB1, PARP1, XRCC5, RPA1, and RPA3—resulted in a significant reduction in tumor sphere formation." (PMID 40230524, 2025). "Inhibition of DDB1 significantly reduced B7-H3 expression, which in turn suppressed CSC properties such as tumor sphere formation and cell migration." (PMID 40230524, 2025). "It has been shown to regulate tumor cell growth and metastasis via a variety of downstream target genes, including Selenbp1, EGFR, Foxa2, CDX2, and DDB1." (PMID 36614938, 2022). "Further tumor grade analyses of multiple clinicopathological features of TCGA-OV samples in the UALCAN database showed that CUL4A and DDB1 expression increased in tumors compared to paracancerous tissue in a non-grade-dependent manner." (PMID 36481655, 2022). "The representative IHC images of normal/tumor and low/high grade tissues from HPA revealed that the degree of staining intensity of CD96, DDB1, IP6K2, PDCL3, TRIM38, and KCNJ15 were in correspondence with our predictions of coefficient." (PMID 34268106, 2021). "In the same hospital, significantly different expressions between matched tumour and healthy adjacent tissues were observed for 6 genes (APEX1, DDB1, ERCC1, NEIL1, PARP1, RPA2) after snap freezing collection." (PMID 27383461, 2016). "Our results indicated that NTZ treatment significantly reduced both tumor sphere formation and cell migration, supporting the notion that NTZ affects CSCs characteristics by regulating B7-H3 expression through the inhibition of the DDB1 TF." (PMID 40230524, 2025). "Transcriptomic data and RT-qPCR findings indicated that PUM2 and HIF3A exhibited high expression levels in normal tissues, while DDB1 showed increased expression in tumor tissues; no significant changes were observed for CUL1, COPS2, and UBE2D3." (PMID 40524221, 2025).
cancer (21 papers, 2011 to 2026). A tumor composed of atypical neoplastic, often pleomorphic cells that invade other tissues. "DDB1 also participates in drug metabolism in cancer therapy and is associated with chemoresistance." (PMID 31842285, 2019). "Targeting the DDB1–AMBRA1–cyclin D1 complex for cancer therapy offers promising strategies to enhance the degradation of cyclin D1." (PMID 40408472, 2025). "Overexpression of CUL4A or CUL4B is a very common sign in many types of cancers in which CUL4A or CUL4B proteins conservatively interacts with DDB1 to recruit other proteins such as RBXs and DACFs, assembling CRL4 E3 ligases 14-19." (PMID 32140073, 2020). "As expected, dCK expression was inversely associated with DDB1 expression (p = 0.013), further indicating that dCK was the effector of DDB1 in cancer cell GEM resistance." (PMID 31842285, 2019). "We examined cultured cancer cell lines and observed high DDB1 expression in multiple PDAC cell lines compared with human pancreatic ductal epithelial (HPDE) cells." (PMID 31842285, 2019). "Components of the CRL4 pathway are known to modulate chemosensitivity in cancer cells, as CUL4 and DDB1 deficiencies exhibit synergistic lethality with camptothecin and UV irradiation." (PMID 30018425, 2018). "These genes are involved in the regulation of cell cycle (CCND1, CDCA5, FOSL1, KDM2A, NUMA1, RHOD), apoptosis (FADD, ORAOV1), or the DNA damage response (DDB1, KAT/TIP60, MUS81, PACS1, RPS3), and several have been implicated in the HPV lifecycle and/or HPV-associated cancers." (PMID 40892869, 2025). "Further supporting this pattern, a positive correlation between SCN scores—a transcriptomic score representing the degree of NE differentiation—and CRBN or DDB1 mRNA expression was also observed in the cancer cell line panels used for CYRS381 sensitivity screening." (PMID 40551250, 2025). "DDB1 and CUL4 associated factor 13 (DCAF13) is a substrate receptor in the CUL4‐DDB1 E3 ligase, and its expression is associated with the prognosis of certain cancers." (PMID 34775691, 2022). "Specific knockdown of CUL4A, CUL4B or DDB1 markedly decreases cancer cell growth." (PMID 32140073, 2020). "DDB1 was reported to participate in apoptosis and chemoresistance regulation in several cancers." (PMID 31842285, 2019). "Based on the potential oncogenic functions of DDB1 in PDAC, we hypothesized that DDB1 might influence cancer cell proliferation, migration, colony formation or apoptosis." (PMID 31842285, 2019). "Prior to the identification of the role of DDB2 in cancers, DDB2 has been well described in the NER process and was identified to form an heterodimeric UV-DDB complex with DDB1 protein to initiate DNA repair." (PMID 36568213, 2022). "Moreover, DDB1 overexpression in malignant cells may lead to resistance to anti-cancer therapy." (PMID 34207079, 2021). "Consistent with the observation that GSPT1 degradation kinetics differ depending on cell type, analysis of TCGA pan-cancer datasets revealed that CRBN and DDB1 mRNA levels were positively correlated with NE gene signature scores and inversely correlated with non-NE gene signature scores." (PMID 40551250, 2025). "The UV‐DDB complex, including DDB1 (LoH: 10.4%) and DDB2 (LoH: 8.0%), facilitates binding of XPC to UVR‐induced lesions, and experimental evidence suggests its knockdown increases tumorigenic potential and reduces overall survival in various cancers." (PMID 35229492, 2022). "Moreover, we found that the genes encoding for the NER-related molecular components of the heterodimer DDB complex (DDB1 and DDB2) were upregulated in cancer patients." (PMID 35740268, 2022). "Intriguingly, we also observed the reversion of the EMT-like phenotype upon examining the cell morphology of DDB1-silenced PDAC cells, implying that DDB1 may play a role in regulating EMT in cancer cells." (PMID 31842285, 2019). "DDB1, which is also involved in NER, is overexpressed in cisplatin resistant cancer cell lines." (PMID 21364753, 2011).
infection (13 papers, 2008 to 2024). The state of being infected such as from the introduction of a foreign agent such as serum, vaccine, antigenic substance or organism. "Chaperones, including the prefoldin and/or the TriC/CCT complexes, emerged as partners of the three CLR4s factors, with their association to DDB1 being decreased upon infection while remaining constant with both SRFs." (PMID 39383947, 2024). "Different binding profiles emerged, with the number of associated partners decreasing upon infection for DDB1 and DCAF11, while DCAF12L1 gained interactors." (PMID 39383947, 2024). "DDB1 silencing in macrophages specifically impaired their susceptibility to infection by SIV and, in addition, impaired the ability of Vpx to enhance infectivity of macrophages by HIV-1." (PMID 18451984, 2008). "A significant rewiring of the CRL4s interaction partners was observed, particularly for DDB1 for which only 26% of the 119 interactors remained constant upon infection, whereas 49% and 65% remained unchanged for DCAF11 and DCAF12L1, respectively." (PMID 39383947, 2024). "The frequency and absolute number of early-stage TFH cells of Ddb1-TaKO SMARTA CD4+ T cells were similar to that of WT counterparts at day 3 after LCMV Armstrong infection." (PMID 34526995, 2021). "As expected, we observed the percentages and cell numbers of GC B cells (FAS+GL7+) were markedly diminished in Ddb1-TaKO mice compared with WT mice at day 8 after infection." (PMID 34526995, 2021). "The DDB1 copurified with untagged PB2 and with PB2-Strep, while it was absent in controls, indicating that the interaction between PB2 and DDB1 can be detected during infection." (PMID 32265326, 2020). "The hepatitis B virus (HBV) regulatory HBx protein is required for infection, and its binding to cellular damaged DNA binding protein 1 (DDB1) is critical for this function." (PMID 32235678, 2020). "Certain other ubiquitination proteins like UBA domain-containing protein 1, DDB1- and CUL4-associated factor 7-like protein were slightly induced upon 12 h of SpltNPV infection." (PMID 28883418, 2017). "In this situation, silencing of DDB1 inhibited the ability of Vpx to enhance macrophage infection by HIV-1." (PMID 18451984, 2008). "At a global level, the remodeling of CRL4 factors upon IAV infection exhibited opposite trends, with a loss of DDB1- and DCAF11-associated factors and a gain of DCAF12L1-associated factors, suggesting a shift toward CRL4DCAF12L1 E3 ubiquitin ligases upon infection." (PMID 39383947, 2024). "While WT SMARTA CD4+ T cells expanded dramatically in response to LCMV Armstrong infection, Ddb1-deficient SMARTA CD4+ T cells failed to expand in the same hosts." (PMID 34526995, 2021). "We next addressed the interaction of PB2 with endogenous DDB1 during infection." (PMID 32265326, 2020). "Interestingly, other NER genes involved in damage recognition, such as DDB1, CETN2, and RBX1, were found to be downregulated during the infection and, in the case of DDB1, data support a putative involvement of CagA." (PMID 33339161, 2020). "Likewise, DDB1 ablation fully restored STAT2 amounts 4 h post infection (lane 4) and partially after 24 h (lane 10)." (PMID 21698215, 2011). "Interestingly, such association decreased upon infection for DDB1 and DCAF12L1, suggesting a shift towards non-proteolytic ubiquitination, consistent with our previous findings on PB2 ubiquitination." (PMID 39383947, 2024). "Our results revealed substantial modulations in the interaction networks of the three factors, DDB1, DCAF11, and DCAF12L1, characterized by a comprehensive reduction in DDB1 and DCAF11 interactions, while DCAF12L1 interactors increased upon infection." (PMID 39383947, 2024). "At day 8 after infection, we found that the frequencies and numbers of total and effector (CD44+ CD62L-) CD4+ T cells derived from Ddb1-TaKO (CD45.1+ CD45.2+) BM was much lower compared with that derived from WT (CD45.2+) BM." (PMID 34526995, 2021).
infection (continued). "Six UPS factors were discovered to be essential for infection with the three viruses (DCAF12L, DDB1, FBXL19, OTUD6A, PAN2, and PHC2)." (PMID 29202037, 2017). "Teasing apart how DENV, or other host response to infection, mediates this change in UBE2A and DDB1 expression would be interesting." (PMID 26566123, 2015). "Of note, RNAi-mediated depletion of DDB1 and TAK1 impaired TNF release after infection with Vpr null virus, suggesting that infection-stimulated TNF release may be another physiological function of DDB1 that is enhanced by HIV-1 Vpr." (PMID 39205287, 2024). "Naïve CD4+ T cells purified from Ddb1-TaKO-SMARTA (CD45.1+) and WT-SMARTA (CD45.1+ CD45.2+) mice were mixed at ratio of 1:1, and then were adoptively transferred into congenic WT recipient mice (CD45.2+) followed by LCMV Armstrong infection." (PMID 34526995, 2021). "However, since silencing of DDB1 in the target cell inhibited SIV infection, this suggests that Vpx usurps DDB1 after infection of the target cell and likely, within the context of the reverse transcription complex." (PMID 18451984, 2008). "Therefore, a prediction is that DDB1 silencing should not inhibit infection of macrophages by HIV-1." (PMID 18451984, 2008). "Since SIV Vpx but not SIV Vpr was essential for macrophage infection, we examined whether fusion of DDB1 to SIV Vpr was sufficient to allow SIV Vpr to counteract the macrophage restriction." (PMID 18451984, 2008). "The partial reduction in DCAF1 levels did not affect the infection of the HIV-1 Vpr+ and HIV-1 Vpr+, suggesting that the Vpr-mediated enhancement of infection in HuT/CCR5 cells did not involve the recruitment of the DCAF1/DDB1/Cul4A complex and proteasomal degradation." (PMID 22570689, 2012).
genetic disorder (2 papers, 2008 to 2024). "In human, a point mutation in the DxR motif (R273H) of DDB2 leads to the XPE genetic disorder by abolishing its interaction with DDB1." (PMID 18551167, 2008). "In XP group E patients, a point mutation in the DxR motif (R273H) of the WD40 domain in DDB2 abolishes its interaction with DDB1 leading to the human genetic disorder XPE." (PMID 18551167, 2008).
cardiovascular disease (1 paper, 2022). "Lastly, dysregulation of GRKs (G-protein-coupled receptor kinases) can be associated with pathological conditions including cardiovascular disease, and GRK5 was found to form a complex with CUL4 through DDB1 and undergo CUL4•DDB1-dependent ubiquitination." (PMID 35327608, 2022).
infectious disease (1 paper, 2021). A disorder directly resulting from the presence and activity of a microbial, viral, or parasitic agent in humans. "Thus, understanding how Ddb1 regulates such differentiation process may shed light on rational vaccine design for infectious disease." (PMID 34526995, 2021).
DDB1 also shares sentences with these, for which no sentence is quoted: non-small cell lung carcinoma (3 papers); Börjeson–Forssman–Lehmann syndrome (2); gastric cancer (2); leukodystrophy (2); male infertility (2); mantle cell lymphoma (2); acute myeloid leukemia (1); autoimmune disease (1); Chung–Jansen syndrome (1); Cockayne syndrome B (1); Cognitive impairment (1); colorectal adenocarcinoma (1); Constipation (1); cutaneous melanoma (1); developmental delay (1); Fanconi anemia (1); glaucoma (1); glioblastoma (1); hematological diseases (1); Hypertension (1); inflammatory bowel disease (1); lipodystrophy (1); medulloblastoma (1); metastatic melanoma (1); mucinous adenocarcinoma (1); myelodysplastic syndrome (1); neuroblastoma (1); plasmacytoma (1); Premature ovarian insufficiency (1); primary effusion lymphoma (1).
A further 8 diseases each share a sentence with DDB1 in 1 paper.